FOXL2NB (FOXL2 neighbor)
Synonyms: C3orf72; FLJ43329
Tractability: No criterion of Open Targets' tractability assessment is met for any kind of drug.
Gene: Protein-coding gene on chromosome 3 (138,947,217 to 138,953,990, forward strand). Ensembl gene ENSG00000206262.
Subcellular location (Human Protein Atlas): Nucleoli fibrillar center
Gene Ontology:
Cellular component: fibrillar center
Genetic constraint (gnomAD): Loss-of-function variants: 11 observed, 6.55 expected, observed/expected ratio (o/e) 1.68, 90% interval 0.99 to 1.95. That is too few expected variants to judge how well the gene tolerates losing a copy. Missense variants: 228 observed, 232.75 expected, observed/expected ratio (o/e) 0.98, 90% interval 0.88 to 1.09. Synonymous variants: 104 observed, 101.17 expected, observed/expected ratio (o/e) 1.03, 90% interval 0.88 to 1.21.
Homologues: Orthologues: chimpanzee FOXL2NB (98% identical), macaque FOXL2NB (85% identical).
Diseases named in the same sentence as FOXL2NB in open-access papers:
FOXL2NB is named in the same sentence as 1 disease in open-access papers, as found by Europe PMC text mining. Sharing a sentence is not in itself a finding about the gene and the disease.
FOXL2NB shares sentences with these, for which no sentence is quoted: cancer (1 paper).